CD4 (CD4 molecule)
Diseases named in the same sentence as CD4 in open-access papers (continued):
Sharing a sentence is not in itself a finding about the gene and the disease.
malaria (continued). "Occurrence of malaria is common in HIV-positive individuals in West Africa and parasitemia increases while CD4 count decreases." (PMID 24713375, 2014). "Recent studies showed that both CD4+ T cells and CD8+ T cells are necessary to mediate immunity to liver stage malaria parasites." (PMID 24620841, 2014). "Sporozoites can induce CD4+ T cells and numerous CD4+ epitopes have been identified in the CSP proteins of both mice and human malaria strains." (PMID 25477870, 2014). "It was shown that PD-1 mediated a reduction in the capacity of parasite-specific CD4+ T cells to proliferate and secrete IFN-γ and TNF-α during the chronic phase of malaria (day 35) indicating exhaustion of these cells." (PMID 24904561, 2014). "These diverse diseases illustrate the central importance of CD4+ T cells in most CD8+ CTL responses; but their precise role in immunity to liver-stage malaria has yet to be defined." (PMID 25426113, 2014). "Vaccination with the pre-erythrocytic malaria vaccine RTS,S induces high levels of antibodies and CD4+ T cells specific for the circumsporozoite protein (CSP)." (PMID 23613845, 2013). "Very few splenic CD4+Foxp3+ T cells expressed IFN-γ in naïve or malaria-infected WT or WSX-1−/− mice and there was only a transient difference in the frequencies and numbers of CD4+Foxp3+ IFN-γ+ cells in WT and WSX-1−/− mice on day 9 of infection." (PMID 23593003, 2013). "The phenotypic analysis of ex-vivo PBMC revealed that CD4+ T cells were found more frequently than CD8+ and CD20+ cells, in both malaria and control individuals." (PMID 24041406, 2013). "The levels of CD4+ and CD25+ regulatory T cells gradually returns to normal level after pregnancy, thus reflecting the pattern of increased incidence of malaria during the first and second trimesters." (PMID 23517907, 2013). "The phenotypic analysis of ex-vivo PBMC revealed that, as expected, CD4+ T cells were found more frequently than CD8+ and CD20+ cells, in both malaria and control individuals." (PMID 24041406, 2013). "T-cell sub-populations (CD4, CD3 and γδTCR) were intracellularly stained for IL-10, IFN-γ and TNF following polyclonal stimulation or stimulated with malaria parasites." (PMID 23294670, 2013). "Also, a malaria pre-clinical study found that the combination of protein in adjuvant with viral vectors in both priming and boosting vaccinations could induce extremely high antibody titres and CD4+ T-cell and CD8+ T-cell responses." (PMID 22970140, 2012). "There was an association between the frequency of RTS,S/AS01E induced CSP-specific CD4+ T cells and protection from clinical malaria, most strongly seen for IFNγ-IL2-TNF+ CD4+ T cells." (PMID 23300801, 2012). "We find that vaccination of malaria-exposed children with RTS,S/AS01E induces IFNγ-IL2+TNF− and IFNγ-IL2+TNF+ CD4+ T cell responses upon in vitro stimulation of whole blood with CSP peptides." (PMID 23300801, 2012). "In this paper, the frequencies of the T cells CD4+CD25+FoxP3+ subsets were similar in Fulani and Mossi ethnic groups at the low and high malaria transmission period." (PMID 22283984, 2012). "While the children in this study had detectable CS-specific IL-2+ CD4+ T cells, these responses were lower than those seen, using a PBMC based assay, in malaria naïve adults vaccinated with RTS,S/AS01 or RTS,S/AS02." (PMID 21494604, 2011). "This suggests that a successful malaria vaccine strategy and formulation should, therefore, promote the induction of strong IFN-γ-producing CD4+ cell responses." (PMID 21303495, 2011). "In summary, in early P. chabaudi malaria, IFN-γ and TNF-α production by spleen cells is intense, short-lasting and mostly dependent on conventional CD4+ T cells." (PMID 21814579, 2011). "This does not seemto be the sole explanation, however, in light of the human malaria DNA, MVAstudies in which we showed very high levels of IFN-γ producing T cells(which were mostly CD4+ cells)." (PMID 21347224, 2011).
malaria (continued). "Thymus (CD4+, and CD25+ T cells) were the major cellular source of IL-10 and TGF-b1 cytokines in malaria infected red blood cells (iRBC) when co-cultured with PBMCs." (PMID 21439091, 2011). "The SUR projected unit cost per person served, by disease, was $6.27 for malaria (nets and training), $15.80 for diarrhea (filters and training), and $9.91 for HIV (test kits, counseling, condoms, and CD4 testing at each site)." (PMID 22189090, 2011). "In contrast, for the malaria infected, BCG vaccinated mice, the TNF-α MFI values of CD4 T cells were strikingly reduced in IFN-γ/TNF-α (70% reduction) and triple positive cells (89%) relative to controls not infected with P. yoelii." (PMID 22205939, 2011). "In acutely infected mice, the type 1 responses from CD4+ and CD8+ T cells are the main participants in the development of both malaria pathogenesis and protective immunity." (PMID 21814579, 2011). "In the present study, we characterized the frequency and quality of naturally acquired IFN-γ producing MSP142 specific CD4 and CD8 T-cell effector memory subsets in children and adults residing in a malaria holoendemic area of western Kenya." (PMID 21935482, 2011). "There are strong animal and human data to support the importance of antibody concentration, CD4+ and CD8+ T cell responses in protection against malaria." (PMID 20937436, 2010). "Flow cytometric analysis also showed a significant increase on CD4+CD25+FoxP3+ T cells producing IFN-γ (P<0.0001), IL-17 (P = 0.0020), TGF-β (P<0.0001) and IL-10 (P<0.0001) in malaria-infected individuals." (PMID 20224778, 2010). "The average proportion of malaria extract-specific proliferating cytotoxic T-cells (CD8+ Ki67+) and proliferating Th cells (CD4+ Ki67+) relative to the general proliferating leucocytes were 4% and 21%, respectively." (PMID 20546583, 2010). "Similar frequencies of IFN-γ+ CD4+ and CD8+ cells were found among splenocytes of malaria-infected anti-IP-10-treated and control mice." (PMID 19343215, 2009). "The goal of RTS,S is to generate neutralizing humoral immunity directed against the sporozoite stage of the malaria parasite before they invade the liver, in addition to inducing CSP-specific CD8 and CD4 Th1+ T cell immunity." (PMID 19691558, 2009). "Following SIV infection naïve CD4+ T cells were depleted more rapidly among the co-infected animals than among the SIV-only animals [regression analysis; SIV-only slope = −1.23, SIV-malaria slope = −2.77, p = 0.048;]." (PMID 19774084, 2009). "CD4+CD25+TNFRII+ T cells were found to express higher levels of Foxp3 than CD4+CD25+TNFRII− T cells, consistent with our earlier observations on TNFRII+ and TNFRII− Treg cells from malaria-exposed individuals." (PMID 19390618, 2009). "CD4+CD25+Foxp3+CD127lo Treg cells were significantly elevated in patients with uncomplicated (UM; n = 17) and severe malaria (SM; n = 16) relative to exposed asymptomatic controls (AC; n = 10)." (PMID 19390618, 2009). "The early immune response of C57BL/6 mice to sporozoite-induced malaria is characterized by a peak of IFN-γ in the serum at day 5 of infection and splenic CD4 T lymphocytes are the major producer of this cytokine at this time point." (PMID 19508725, 2009). "The incidence of symptomatic malaria episodes, severe or uncomplicated, and the corresponding parasite density is higher in HIV-1 infected individuals with low CD4 count." (PMID 18647387, 2008). "Relative risks for malaria in HIV-infected persons, derived from literature review, were applied to the HIV-infected population in each country, by age group, stratum of CD4 cell count, and urban versus rural residence." (PMID 16229771, 2005). "Co-trimoxazole prophylaxis should be initiated regardless of CD4 cell count or WHO clinical stage in settings where malaria or severe bacterial infections are highly prevalent." (PMID 41557672, 2026).
malaria (continued). "Ivory Coast and Republic of Congo guidelines recommended starting CTX in all PWH irrespective of the CD4 count, based on the high prevalence of malaria or severe bacterial infections." (PMID 40158188, 2025). "Despite the evidence that PfCSP-specific CD4+ and potentially also CD8+ T cells play a role in protection from malaria, little is known about the molecular characteristics of TCRs that mediate PfCSP binding to inform the design of vaccines with the potential to mediate more potent protection." (PMID 40637713, 2025). "This strategy has demonstrated protective benefits against malaria regardless of CD4 count or clinical stage." (PMID 40236626, 2025). "Studies have shown that LHWs, with adequate training, can reliably perform POCT services for rapid HIV, malaria, hepatitis, syphilis, urinary Mycobacterium tuberculosis lipoarabinomannan (urine TB LAM), cryptococcal antigen, haemoglobin, CD4 cell count and near POC molecular instruments." (PMID 41460810, 2025). "We included an evaluation of CD4 and CD8 T-cell responses to human cytomegalovirus (CMV), another chronic viral infection, to ask whether the reported malaria-induced immune perturbations were EBV-specific or reflected a more global suppression." (PMID 41285032, 2025). "In addition to malaria, Nigeria faces a significant burden of the Human Immunodeficiency Virus (HIV), a viral infection that undermines the immune system by attacking CD4+ T cells, which are essential for immune defence." (PMID 40236626, 2025). "Here, we utilized single cell RNA sequencing to identify putative cell surface markers for Tr1 cells in the blood of children living in malaria-endemic Uganda and establish that CXCR6+ CD127− memory CD4+ T cells enrich for high-confidence, bona fide Tr1 cells in this setting." (PMID 41000872, 2025). "Hence, these results show that CD4+ T cell–intrinsic type I IFN signaling is required for optimal IL-10 and IFN-γ production as well as Tr1 cell development in vivo in experimental malaria." (PMID 37781920, 2023). "We observed that boosting the live malaria vaccine with MCMV including a Plasmodium antigen led to longer protection from P. chabaudi parasitemia, and can be used to promote maintenance of antigen-specific CD4 T cells." (PMID 37205446, 2023). "We concluded that P2RX7-mediated metabolic reprogramming of CD4+ T cells for aerobic glycolysis is a general phenomenon, not restricted to malaria, which is a key event for Th1 differentiation." (PMID 36993971, 2023). "The next most popular tests in national guidance are the HIV serology screening tests (24 and 25 of 26 countries), the CD4 count (24/26, suggesting that countries largely select CD4 enumeration to be done in a laboratory facility despite available POC format) and malaria microscopy (25/26)." (PMID 37200237, 2023). "Some of these studies also examined B cells ex vivo and concluded that they did not activate CD4+ T cells during malaria; however, they specifically isolated the CD11c- subset, likely excluding the activated B cells that are most likely to serve as APCs." (PMID 36715223, 2023). "We demonstrated recently that B cells, rather than DCs, are the principal activators of CD4+ T cells in murine malaria." (PMID 36715223, 2023). "We also found that DCs remained competent to activate CD4+ T cell responses to soluble antigens in hosts with malaria, suggesting no global dysfunction occurs." (PMID 36715223, 2023). "Our study also shows that this second expansion phase of malaria‐specific CD4+ T cells is not a direct effect of IL‐27 inhibition, since inhibition with anti‐IL‐27 Ab starting 11 days of infection had no such effect." (PMID 37855243, 2023). "In contrast, multigravid women had higher percentages of CD4+ T cells that produced TNFα in the absence of IFNγ and IL-10, and these cells were correlated with protection against malaria in pregnancy." (PMID 37634385, 2023).
malaria (continued). "CD4+ T cell STING is required for optimal IFN-γ and IL-10 production in experimental malaria." (PMID 37781920, 2023). "Follow-up studies from this group demonstrated that both CD4+ T cells and CD8+ T cells from malaria-infected individuals adopted a Tr1-like phenotype and cytokine profile, illustrated by high expression of LAG-3 and co-inhibitory receptors accompanied by production of IL-10, IFN-γ, and granzyme B." (PMID 36389662, 2022). "Our study highlights IFNγ+CD4+ T and γδ T cells co-producing IFNγ and TNF as well as anti-malarial antibodies against blood-stage proteins as correlates of varying strength of naturally acquired immunity in lifelong residents of a malaria-endemic area." (PMID 35922467, 2022). "Some have suggested that malaria may promote HIV replication and accelerate the decline in CD4+ T lymphocytes." (PMID 35778766, 2022). "Taken together, CD4+ T cells producing IFNγ, with or without TNF co-production, are associated with parasite control in lifelong malaria-exposed individuals." (PMID 35922467, 2022). "However, there was positive correlation between CD4 counts with RBC and Hgb in malaria-HIV co-infected." (PMID 35245289, 2022). "Complicated malaria – as he is HIV-positive and defaulted with an unknown CD4, he should be assessed as complicated malaria." (PMID 35261261, 2022). "It was observed that number of CD4+ T cells expressing ICOS gradually increased in both sets of animals infected with either lethal or non-lethal malaria parasite." (PMID 35109868, 2022). "Using a bespoke flow cytometry assay we measured intracellular IFN-γ, IL-10, IL-17A expression and phenotyped CD4+ and CD8+ T cell effector memory subsets specific to EBNA1 for eBL patients compared to two groups of healthy children with divergent malaria exposures." (PMID 34771539, 2021). "CD4+ Th cells can modulate the type of immune response, and CD8+ Tc cells are essential for the clearance of intracellular pathogens and serve as targets for malaria vaccine research." (PMID 35127555, 2021). "In addition, eBL children seem to have developed more IL-17A expressing CD4+ and CD8+ T cells compared to Kisumu children who also resided in malaria holoendemic areas." (PMID 34771539, 2021). "Malaria-specific memory T cells (both CD8+ and CD4 + T cells) are mainly involved in patrolling, conducting continuous surveillance and deploying quick recruitment to the site(s) of infection thereby providing a rapid, effective, specific and durable protection against subsequent malaria infections." (PMID 34666102, 2021). "This study aims to evaluate the CD4+ and CD8+ T cells, leucocytes subpopulations, IL-6, IL-10 and biomarkers of oxidative stress among children infected with varying grades of malaria attending the University of Abuja Teaching Hospital and National Hospital, Abuja, Nigeria." (PMID 35223394, 2021). "The mean whole blood CD4+ T cell count of children without malaria, with mild, moderate and severe malaria was 710 ± 111 cells/mm3, 628 ± 105 cells/mm3, 592 ± 82 cells/mm3 and 390 ± 50 cells/mm3, respectively." (PMID 35223394, 2021). "In both HbAS and HbAA children, the frequency of memory CD4+ T cells did not correlate with any of the malaria protection features." (PMID 33763229, 2021). "Whether the critical protective IFN-γ derives from CD4+ TH1 cells, TFH, or CD8+ T cells in producing protective IFN-γ during malaria remains unknown, as do the specific mechanisms by which IFN-γ contributes to parasite control." (PMID 32043415, 2020). "In summary, LAG-3 blockade contributes to rescuing malaria-induced CD4+ T cell dysfunction in PD-L1-/- mice, but does not appear to modulate their ability to differentiate into various functional and memory subsets of T cells." (PMID 33519801, 2020). "Our data show that within the Ag-specific CD4 T cell compartment, pTfh cells but not non-pTfh show a kinetic and functional response to the malaria vaccine." (PMID 32342859, 2020).
malaria (continued). "Both CD4+ T and CD8+ T cells play a major role in protective immunity against malaria." (PMID 33298881, 2020). "This means that malaria/HIV co-infections could worsen the immune response to both diseases due to enhanced T-cell activation and may explain the low CD4 count in patients coinfected with both diseases." (PMID 33175844, 2020). "However, in PBMC of malaria patients we only observed an increase of PD1−LAG-3+ CD8+ T cells when compared to the frequency of PD1−LAG-3+ CD8+ and CD4+ T cells in healthy controls." (PMID 32983106, 2020). "Upregulation of the CD4 co‐receptor on CD4+ T cells has not been described previously in human malaria or in experimental mouse malaria." (PMID 33282291, 2020). "The new guidelines also recommend that CTX prophylaxis should be continued regardless of CD4 cell count or WHO clinical stage in settings where malaria and/or severe bacterial infections are prevalent." (PMID 33175844, 2020). "We have previously analyzed the protective role of T cells or immunological molecules, or both, against blood stage malaria, and found CD4 and CD8 T cells to be important but not essential for protection against primary infection with blood-stage PyNL." (PMID 32664476, 2020). "CD4 and CD8 T cells producing IFNg, interleukin 2 (IL2) and tumor necrosis factor alpha (TNFa) were detected in peripheral blood after immunization of malaria naïve volunteers, however, their levels rapidly declined over time and were not correlated with protection." (PMID 32662772, 2020). "The predictors of placental malarial parasitaemia and eventual MTCT of HIV infection in this study included, gestational age at booking, CD4 counts, treatment of symptomatic malaria with ACT and number of doses of IPT for malaria which are comparable to other studies." (PMID 32103782, 2020). "The increased level has been associated with the predominance of CD8+ thereby, inhibiting CD4+ production as seen in HIV-infected pregnant women with malaria coinfection compared to HIV seropositive pregnant participants without malaria." (PMID 33193759, 2020). "The WHO recommends the continuation of cotrimoxazole prophylaxis regardless of CD4 cell count or WHO clinical stages in settings where malaria is highly prevalent." (PMID 33292761, 2020). "In malaria patients we observed an increase of TIGIT on bulk CD8+ and CD4+ T cells." (PMID 32983106, 2020). "Although earlier studies on the role of CD4+Foxp3+ Tregs in immunity to malaria were not conclusive, recent findings in mice infected with Plasmodium chabaudi AS or P. yoelii support the notion that Tregs suppress Th1 as well as Tfh cell responses." (PMID 30915078, 2019). "In contrast to CD8 T cells, the role of CD4 T cells in protection against malaria is not well understood." (PMID 31231377, 2019). "The exact role of T-bet+Foxp3+ Tregs in suppressing effector CD4+ T cell responses during malaria has not yet been resolved." (PMID 30915078, 2019). "In this study, we found that CD4+PD-1+ and CD8+CTLA-4+ could also predict parasitemia levels in the asymptomatic malaria group." (PMID 31316497, 2019). "The current study findings showed that individuals living with HIV within age brackets below 5 years and those between 10 and 19 years had the highest malaria density of about 95,000/ μL regardless of their CD4 T-cells status." (PMID 31354844, 2019). "Together, our findings indicate Th1-like CD4+T-bet+Foxp3+ Tregs that express CXCR3 are induced during acute blood-stage malaria and suggest CXCR3 expression on CD4+ Th1 cells may contribute to their migration to the spleen." (PMID 30915078, 2019). "Previous studies demonstrated CXCR3 is expressed on CD4+ T cells in the spleen during malaria, but the phenotype was not defined." (PMID 30915078, 2019). "An insignificant negative correlation, however, between CD4 T-cells count and malaria parasite densities was noted (p = 0.169)." (PMID 31354844, 2019).